MMP27 (matrix metallopeptidase 27)
Description:
Matrix metalloproteinases degrade protein components of the extracellular matrix such as fibronectin, laminin, gelatins and/or collagens.
Synonyms: MMP-27
Tractability: Small molecule: it belongs to a druggable protein family. Antibody: UniProt predicts a signal peptide or a membrane-spanning region; its Gene Ontology location is reachable by antibodies, with medium confidence.
Gene: Protein-coding gene on chromosome 11 (102,691,487 to 102,705,769, reverse strand). Ensembl gene ENSG00000137675.
Subcellular location: Endoplasmic reticulum
Gene Ontology:
Molecular function: metalloendopeptidase activity; metallopeptidase activity; zinc ion binding
Biological process: collagen catabolic process; extracellular matrix organization; proteolysis
Cellular component: endoplasmic reticulum; extracellular matrix
Genetic constraint (gnomAD): Loss-of-function variants: 42 observed, 41.06 expected, observed/expected ratio (o/e) 1.02, 90% interval 0.8 to 1.32. The upper end of that interval is the gene's LOEUF score, 1.32, which puts it in group 5 of 6, group 1 being the genes least tolerant of losing a copy. Missense variants: 625 observed, 570.03 expected, observed/expected ratio (o/e) 1.1, 90% interval 1.03 to 1.17. Synonymous variants: 203 observed, 193.58 expected, observed/expected ratio (o/e) 1.05, 90% interval 0.93 to 1.18.
Homologues: Orthologues: chimpanzee MMP27 (99% identical), macaque MMP27 (96% identical), dog MMP27 (83% identical), pig MMP27 (83% identical), rabbit MMP27 (82% identical), guinea pig MMP27 (79% identical), mouse Mmp27 (76% identical), rat Mmp27 (76% identical), zebrafish mmp13b (43% identical), zebrafish mmp30 (38% identical), zebrafish mmp25b (32% identical), Drosophila melanogaster Mmp1 (30% identical), and 9 more. Paralogues in human: MMP10 (47% identical), MMP3 (47% identical), MMP1 (45% identical), MMP8 (44% identical), MMP12 (43% identical), MMP13 (43% identical), MMP20 (38% identical), MMP2 (36% identical), MMP24 (35% identical), MMP15 (34% identical), MMP16 (34% identical), MMP14 (34% identical), and 11 more.
Diseases named in the same sentence as MMP27 in open-access papers:
MMP27 is named in the same sentence as 12 diseases in open-access papers, as found by Europe PMC text mining. Sharing a sentence is not in itself a finding about the gene and the disease. The quoted sentences say what the papers report.
breast carcinoma (4 papers, 2009 to 2025). "Although the expression of MMP-27 mRNA was lower in breast cancer samples, its protein showed a diverse expression pattern in the analyzed samples." (PMID 19531263, 2009). "Showing a statistical significant difference in the expression level between normal breast and breast cancer tissue grade 2 and 3 it seems possible, that some of the putative bandages of MMP-27 and -28 are playing a role in breast cancer development." (PMID 19531263, 2009). "For instance, MMP27, while not directly linked to breast cancer, belongs to the matrix metalloproteinase family associated with tumour progression." (PMID 40925719, 2025). "The only tumor entity in which MMP-27 has also been subject to broader research is breast cancer." (PMID 36011038, 2022). "The results showed that MMP9, MMP12, MMP15, and MMP27 groups were all highly variable (p < 0.01), whereas the other groups were not markedly different, indicating that these genes may play important roles in the occurrence and development of breast cancer." (PMID 35069702, 2021).
melanoma (1 paper, 2013). A malignant, usually aggressive tumor composed of atypical, neoplastic melanocytes. "Exons 1, 2, 3, 8 and 9 of the MMP27 gene were selected for sequencing as they have been shown to carry somatic mutations in melanomas." (PMID 24137342, 2013). "In particular, mutations of the MMP27 gene have been observed in melanoma." (PMID 24137342, 2013).
migraine (1 paper, 2022). "Also, our combined gene-based analysis identified three migraine-associated MMPs, including MMP7, MMP20 and MMP27." (PMID 35546551, 2022).
oral cancer (1 paper, 2022). "MMP-27, RANKL and OPG were analyzed in samples of 119 oral cancer patients (TMA cohort)." (PMID 36011038, 2022).
thyroid cancer (1 paper, 2013). "The MMP27 gene was analyzed for mutation in ATC in the present study as we had already previously analyzed the second gene, MMP8, in thyroid cancer." (PMID 24137342, 2013). "The present study reports for the first time the mutational status of the GNA11, MMP27, FGD1, TRRAP and GRM3 genes in thyroid cancer." (PMID 24137342, 2013). "No novel MMP27 somatic mutations were identified in 12 thyroid cancer cell lines and 15 ATC tumor samples." (PMID 24137342, 2013). "The mutation status in the GNA11, MMP27, FGD1, TRRAP and GRM3 genes has not been studied in thyroid cancer." (PMID 24137342, 2013). "In conclusion, the present findings suggested that genetic alterations in the GNA11, MMP27, FGD1, TRRAP and GRM3 genes may not be significant in the tumorigenesis of thyroid cancer." (PMID 24137342, 2013).
urolithiasis (1 paper, 2023). Stone(s) within the urinary tract. "For LASSO regression analysis, six variables, MMP1, MMP3, MMP9, MMP10, MMP27 and, MMP28, were screened as diagnostic markers for urolithiasis." (PMID 37006258, 2023).
tumor (11 papers, 2009 to 2025). "Following carboplatin treatment, CAFs increased their expression of numerous MMP genes (Mmp2, Mmp3, Mmp13, Mmp14, Mmp27); proteases involved in the degradation of the tumor-supporting matrix." (PMID 37660083, 2023). "Statistical analysis of in silico data revealed decreased MMP-27 mRNA expression to be strongly associated with the pT4a-stage in OSCC, indicating invasive tumor growth with infiltration of adjacent anatomical structures." (PMID 36011038, 2022). "Altogether, we suggest a beneficial tumor-suppressive role for MMP-27, whereas loss of MMP-27 goes along with aggressive tumor behavior, particularly with osteolytic bone invasion." (PMID 36011038, 2022). "In summary, we suggest that MMP-27 expression functions as a tumor suppressor, whereas decreased MMP-27 expression is associated with poor differentiation and increased tumor invasiveness, particularly bone invasion, in OSCC." (PMID 36011038, 2022). "Several genes showed progressive increases during tumor growth, including Mmp2, Mmp3, Mmp13 and Mmp16, whereas Timp2 and Mmp27 showed more dynamic fluctuations in expression." (PMID 25848906, 2015). "In contrast, MMP-7 and MMP-27 mRNA showed a weaker expression in tumor samples compared to healthy tissue." (PMID 19531263, 2009). "In addition to evaluation of traditional clinicopathological parameters like tumor grading and staging, histological pattern of invasion (WPOI grade 1–5) and the three different biomarkers MMP-27, RANKL and OPG were investigated for significant associations with bone invasion and patient survival." (PMID 36011038, 2022). "According to the expression pattern analysis, all the MMPs upregulated in CRC showed lower promoter methylation, except MMP11, while all the MMPs downregulated in CRC showed higher promoter methylation in tumor samples compared with normal samples, except for MMP15 and MMP27." (PMID 34830271, 2021). "The results showed that 10 MMP genes were upregulated and MMP27 was downregulated in nonmetastatic tumour samples compared with normal controls." (PMID 31996191, 2020).
cancer (9 papers, 2012 to 2023). A tumor composed of atypical neoplastic, often pleomorphic cells that invade other tissues. "It appears that human melanomas are frequently associated with mutations in Mmp8 and Mmp27 genes leading to loss-of-function and enhanced progression of the cancer." (PMID 22822400, 2012). "There is no further data indicating that such a modification occurs for MMP-27 in cancer, but there are reports that, for instance, MMP-14 is phosphorylated in metastatic ovarian cancer compared to its wild-type." (PMID 36011038, 2022). "EGFR, ERBB3, MMP20, MMP27, MCL1, BCL2A1 and BAK1 appear to be important genes for cancer progression due to their frequent association with recurrent cancer-related genes in women." (PMID 31205821, 2019). "From various cancer formation and metastasis signals, it can be seen that a set of matrix metalloproteases (MMPs) (MMP27, MMP23B, THBS2, MMP13, MMP11) as well as the MMPs receptor ITGB3 were inhibited in GX0101-infected CEFs." (PMID 27200301, 2016). "In addition, we observed a decline in MMP-27 protein expression with a higher T-stage in our patient cohort; a significant number of bone invasive pT4a-stage cancers had low MMP-27 presence compared to pT2 and pT3 OSCC." (PMID 36011038, 2022). "Seven MMPs (MMP7, MMP11, MMP12, MMP13, MMP24, MMP27, and MMP28) had an AUC of greater than 0.95 for at least one cancer type." (PMID 31200666, 2019). "Some MMPs had very high numbers of transcripts present (gene cluster A), while six MMPs in gene cluster C (MMP27, MMP21, MMP20, MMP26, MMP23A, and MMP8) featured scant numbers of transcript copies across any cancer tissue." (PMID 31200666, 2019). "Other members of the MMP family (MMP15, MMP16, MMP19, and MMP27) showed no differential expression between pancreatic normal and cancer tissues." (PMID 37821678, 2023). "Interestingly, MMP2, MMP7, MMP23B, MMP27 and MMP28) are significantly down-regulated in seven to nine cancer types." (PMID 31200666, 2019). "However, the role of MMP-27 in cancer is quite unclear; to the best of our knowledge, no study has yet been done on its role in OSCC." (PMID 36011038, 2022).
infection (1 paper, 2023). The state of being infected such as from the introduction of a foreign agent such as serum, vaccine, antigenic substance or organism. "Our study found MMP27 is upregulated during H37Rv infection." (PMID 36992931, 2023).
MMP27 also shares sentences with these, for which no sentence is quoted: Co-infection (1 paper); generalized epilepsy (1); Oral Squamous Cell Carcinoma (1).